TMPRSS12 (transmembrane serine protease 12)
Description:
Required for male fertility (By similarity). Plays a critical role in sperm capacitation and acrosome reactions during fertilization, and also plays a role in the regulation of proteins involved in spermatogenesis (By similarity). Regulates protein pathways that promote chromosomal synapsis formation, double-strand break repair, formation of the inner mitochondrial membrane cristae and apoptosis in developing sperm (By similarity). Required for normal sperm motility and binding to the zona pellucida, potentially via a role in ADAM3 protein maturation (By similarity).
Synonyms: MGC57341; CT151
Tractability: Antibody: UniProt places it where antibodies can reach, with high confidence; UniProt predicts a signal peptide or a membrane-spanning region; its Gene Ontology location is reachable by antibodies, with medium confidence.
Gene: Protein-coding gene on chromosome 12 (50,842,920 to 50,887,884, forward strand). Ensembl gene ENSG00000186452.
Subcellular location: Cell membrane; Cytoplasmic vesicle, secretory vesicle, acrosome
Gene Ontology:
Molecular function: serine-type peptidase activity; serine-type endopeptidase activity
Biological process: acrosome assembly; positive regulation of sperm capacitation; protein processing; spermatogenesis; proteolysis
Cellular component: plasma membrane; acrosomal vesicle
Genetic constraint (gnomAD): Loss-of-function variants: 25 observed, 23.36 expected, observed/expected ratio (o/e) 1.07, 90% interval 0.78 to 1.49. The upper end of that interval is the gene's LOEUF score, 1.49, which puts it in group 6 of 6, group 1 being the genes least tolerant of losing a copy. Missense variants: 417 observed, 405.27 expected, observed/expected ratio (o/e) 1.03, 90% interval 0.95 to 1.12. Synonymous variants: 134 observed, 142.12 expected, observed/expected ratio (o/e) 0.94, 90% interval 0.82 to 1.09.
Homologues: Orthologues: chimpanzee TMPRSS12 (99% identical), macaque TMPRSS12 (92% identical), rabbit TMPRSS12 (69% identical), dog TMPRSS12 (68% identical), pig TMPRSS12 (68% identical), rat Tmprss12 (59% identical), guinea pig TMPRSS12 (59% identical), mouse Tmprss12 (58% identical). Paralogues in human: PRSS48 (28% identical), OVCH1 (27% identical), PLG (26% identical), PRSS27 (26% identical), PLAT (25% identical), PRSS33 (24% identical), KLK15 (24% identical), PRSS50 (23% identical), GZMM (21% identical), KLK9 (21% identical), PRSS57 (21% identical), PRSS37 (16% identical), and 2 more.
Diseases named in the same sentence as TMPRSS12 in open-access papers:
TMPRSS12 is named in the same sentence as 6 diseases in open-access papers, as found by Europe PMC text mining. Sharing a sentence is not in itself a finding about the gene and the disease. The quoted sentences say what the papers report.
Infertility (3 papers, 2020 to 2025). "While the precise molecular mechanisms are still under investigation, the infertility phenotypes associated with Tmprss12 and Prss55 knockouts highlight their potential as targets for male contraception." (PMID 40764777, 2025). "Considering the oligospermia, asthenospermia and infertility phenotype exhibited by Tmprss12−/− mice and the deleterious missense mutation of Tmprss12 found in infertile men with dyszoospermia, Tmprss12 is likely to be a potential pathogenic gene in these patients." (PMID 35547804, 2022). "This study aimed to evaluate the potential of human PRSS55 and human TMPRSS12 to rescue the infertility phenotypes observed in their respective mouse knockout models, thereby establishing humanized mouse models for future contraceptive drug testing." (PMID 40764777, 2025). "This study investigated whether human orthologs of two mouse testis-specific serine proteases, PRSS55 and TMPRSS12, both essential for male fertility in mice, could functionally rescue the infertility phenotypes of their respective knockout mouse lines." (PMID 40764777, 2025). "Therefore, this study aimed to investigate the efficacy of human PRSS55 and human TMPRSS12 in rescuing the infertility phenotypes of their respective knockout mouse lines." (PMID 40764777, 2025). "TMPRSS12 and its downstream molecules could become potential targets for the clinical diagnosis and treatment of infertility." (PMID 35547804, 2022). "In this study, we generated Tmprss12 KO mice using the CRISPR/Cas9 system, and these KO mice were infertile primarily due to failure of spermatozoa to migrate through the UTJ." (PMID 32529245, 2020). "Conversely, the human TMPRSS12 transgene failed to rescue infertility in Tmprss12 knockout mice under the conditions tested." (PMID 40764777, 2025).
head and neck squamous cell carcinoma (1 paper, 2022). A squamous cell carcinoma that arises from any of the following anatomic sites: lip and oral cavity, nasal cavity, paranasal sinuses, pharynx, larynx, and salivary glands. "However, a study in head and neck squamous cell carcinoma described a characteristic promoter methylation pattern of ZNF10, TMPRSS12, ERGIC2, and RNF215 genes, which was proposed as a biomarker of response to radiotherapy treatment." (PMID 35359376, 2022).
male infertility (1 paper, 2020). The inability of the male to effect fertilization of an ovum after a specified period of unprotected intercourse. "Because Tmprss12 is conserved among mammals, including humans, our results may explain some genetic cases of idiopathic male infertility, and TMPRSS12 and its downstream cascade may be novel targets for contraception." (PMID 32529245, 2020). "Our discovery that Tmprss12 plays dual functions in fertility can be useful in explaining idiopathic male infertility, and since TMPRSS12 is conserved among mammals, including human, TMPRSS12 may be a novel target for the identification of male contraceptive molecules." (PMID 32529245, 2020).
TMPRSS12 also shares sentences with these, for which no sentence is quoted: asthenospermia (1 paper); colon cancer (1); oligospermia (1).